IGF2 (insulin like growth factor 2)
Diseases named in the same sentence as IGF2 in open-access papers (continued):
Sharing a sentence is not in itself a finding about the gene and the disease.
cancer (continued). "This condition likely led to uncontrolled IGF2 upregulation that enhanced cancer growth and survival by binding to IGF1R." (PMID 32075092, 2020). "For these cancers, it has been proposed the name of “IGF-2-omas” to highlight this commonly shared feature." (PMID 33266015, 2020). "To analyze the allelic expression of imprinted genes in cancer, we selected 5 imprinted genes GNAS, GRB10, SNRPN, IGF2, and IGF2R which were mostly reported to be associated with cancer." (PMID 32448196, 2020). "DNA methylation of the IGF2 promoter region is impaired in cancer cells with IGF2 overexpression, suggesting that epigenetic alteration is one of the mechanisms of transcriptional IGF2 activation." (PMID 33293585, 2020). "In particular, dysregulation in the methylation of the IGF2 gene promoters occurs in several cancers including BC and this altered methylation leads to different clinical features in BC disease." (PMID 33216823, 2020). "Specifically, both IGF2 and the fetal A isoform of IR are frequently overexpressed in cancers, resulting in the activation of a loop that leads to a potentiation of cancer phenotype." (PMID 32796774, 2020). "Using these results, imprinted genes GNAS, GRB10, and SNRPN were identified as the more efficient cancer biomarkers over IGF2 and IGF2R, specifically using our QCIGISH method." (PMID 32448196, 2020). "These examples indicate how extensive and important a role insulin-like growth factor 2 plays in the cancer process." (PMID 32850012, 2020). "The insulin-like growth factor 2 mRNA binding protein (IGF2BP) family has been reported to be involved in a variety of human malignant tumours." (PMID 33246429, 2020). "Another interesting matter is the presence of IGF2 LOI in cancer stem cells isolated from all of the studied CRC cell lines (HT29, HRT18, and HCT116)." (PMID 31623387, 2019). "H19 and insulin-like growth factor 2 (IGF2) usually jointly accelerate cancer development of mammary and pulmonary tumors." (PMID 31744046, 2019). "Combined, these results argue for the existence of a regulatory network between two imprinted genomic loci, in which miR-493-5p rescue can overcome the oncogenic activity of IGF2-derived intronic miR-483 in cancer cells exhibiting IGF2-miR-483 LOI." (PMID 31320614, 2019). "In contrast to evidence in normal embryonic tissues, IGF2BP3 promotes IGF2 mRNA translation in cancer cells by binding its 3′-UTR, leading to the increased activation of IGF signaling." (PMID 32010687, 2019). "In CRC, similarly to other cancers, IGF2 promotes cancer cell growth through several types of receptors, mainly IGF1R and AKT phosphorylation, as well as IR-A." (PMID 31623387, 2019). "To better define the metabolic effect of IR-A, which is the receptor principally involved in IGF2 action in cancer cells, we used MCF7 cells where the IGF1R was stably knocked-out by CRISPR/Cas technology and stably overexpressed the IR-A (MCF7IGF1R-ve/IR-A)." (PMID 31480557, 2019). "Many studies have shown that the IGF2 mRNA-binding protein 2 (IGF2BP2) plays oncogenic roles in cancers." (PMID 31852504, 2019). "Our goal was to understand the IGF2 role in ACC biology by focusing in several cancer hallmarks, including cell proliferation, viability, invasion, and metabolism." (PMID 31378849, 2019). "IGF2BP2 mediates stabilization of HMGA1 mRNA and production of IGF2 which synergistically drive cancer progression." (PMID 31852504, 2019). "Igf2 is known to regulate adult hematopoetic stem cell activity and Sulf1expression decreases proliferation and migration in cancer cell lines." (PMID 29676999, 2018). "In TC, IR is predominantly expressed as the “pro-mitogenic” isoform A (IR-A), which binds—with high affinity—to not only insulin, but also to IGF-2, which is produced by cancer cells in autocrine manner." (PMID 30513575, 2018).
cancer (continued). "Beside its growth-promoting and beneficial functions during embryonic development and placental growth, a role for IGF2 has been clearly established in both cancer and cardiovascular diseases." (PMID 29946151, 2018). "IGF2BP3 is synthesized de novo in cancer, where it promotes proliferation, drug resistance, and metastasis via both IGF2-dependent and IGF2-independent mechanisms." (PMID 29731738, 2018). "The known target mRNA of this RBP, IGF2, has defined roles in cell division and hepatocellular physiopathology and is believed to drive cancer cell dedifferentiation and hepatocarcinogenesis." (PMID 29736175, 2018). "The IR phosphorylation, due to increased IGF-2 activates a growth-promoting autocrine loop in cancer cells." (PMID 30453495, 2018). "These novel findings, in conjunction with prior studies of IGF2 in cancer, further substantiate that IGF2 is a biological mediator of an aggressive cancer phenotype and a potential therapeutic target." (PMID 29455465, 2018). "It has been proposed that LOI of IGF2 is a common feature of cancer stem cells including those in PCa and that LOI enhances stemness, self‐renewal, and resistance against chemo‐ and radiotherapy." (PMID 29239100, 2018). "A main observation of this study was the finding that IGF2 expression in PCa, in marked contrast to many other cancers, was reduced in most of the tumors compared to adjacent, morphologically normal tissues." (PMID 29239100, 2018). "This autocrine loop involving IGF-2 and the isoform IR-A is activated in different cancers and particularly in the PDTC histotypes, and exerts a crucial role in regulating stem-like properties, metastases, and resistance to therapies." (PMID 30513575, 2018). "Evidence from cancers other than PDAC suggest that usage of neutralizing agents against IGF-1/IGF-2 can be a promising approach." (PMID 29475434, 2018). "The IGF2/H19 domain has been well investigated because IGF2 LOI is a common event in many cancers, including CRC." (PMID 30509319, 2018). "Strong evidence has proved that aberrant H19 DMR/ICR methylation by controlling CTCF6 binding sites led to LOI of IGF2/H19 and finally resulted in abnormal expression of IGF2/H19 in diverse human cancers." (PMID 29643943, 2018). "The IR-A overexpression, and the increased IR-A:IR-B ratio, are mechanisms that promote the mitogenic response of cancer cells to insulin and IGF-2, which is produced locally by both epithelial and stromal cancer cells." (PMID 30453495, 2018). "Specifically, IGF-2 stimulates the self-renewal properties of the thyroid precursors, thus favoring cancer thyrosphere expansion." (PMID 30513575, 2018). "We conclude that the pro-proliferative effect of IMP2 in most cancer derived cell lines is mediated predominantly by upregulation of IGF2 production and suppression of Grb14 and IGFBP2 polypeptide abundance which together facilitate IGF2 signaling." (PMID 28753127, 2017). "Taken together, the results provided the first evidence showing that Id1-induced IGF2 from cancer cells can activate stromal fibroblasts in a paracrine manner, and stimulate them to produce VEGF as well as to adopt a more cancer-promoting phenotype." (PMID 28186102, 2017). "The gene encoding the Insulin-like Growth Factor 2 mRNA binding protein 2/IMP2 is amplified and overexpressed in many human cancers, accompanied by a poorer prognosis." (PMID 28753127, 2017). "Expression of the imprinted gene IGF2 is often dysregulated in human cancer and the molecular mechanisms are still not fully understood." (PMID 29017567, 2017). "We investigated the correlation between oesophageal tumour IGF2 expression and fibroblast VEGF expression by isolating cancer-associated fibroblasts (CAFs) and NEFs from 11 cases of ESCC and adjacent normal tissues, respectively." (PMID 28186102, 2017).
cancer (continued). "Direct evidence for the role of LOI and cancer comes from the mouse model, in which biallelic expression of Igf2 present on an Apc(Min) background has an increased incidence of colorectal cancers." (PMID 28883545, 2017). "Overexpression of the oncofetal insulin-like growth factor 2 mRNA-binding protein 2 (IMP2/IGF2BP2) has been described in different cancer types." (PMID 29163784, 2017). "The growth hormone insulin-like growth factor 2 (IGF2) signaling pathway is a promising target to overcome drug resistance in many cancers." (PMID 28521298, 2017). "This indicates that IMP2 promotes cancer cell growth both by enabling cells to produce more IGF2 and by suppressing inhibitors of IGF2 action." (PMID 28753127, 2017). "ACC is an endocrine tumor where the massive secretion of IGF2 acts in an auto/paracrine loop to sustain cancer cell proliferation, via activation of both insulin and IGF-1R pro-survival intracellular pathways." (PMID 27391065, 2016). "By examining allelic expression using an IGF2 exon 9 SNP, we have shown that IGF2 imprinting is lost in CSCs, including CSCs derived from two cancer cell lines in which IGF2 is monoallelically expressed." (PMID 27275535, 2016). "IGFBP-6 has a high affinity for binding IGF-2 and is able to inhibit the growth of various cancer cells and activated apoptosis pathways as an IGF-antagonist." (PMID 27464624, 2016). "p62/IMP2 is an oncofetal protein that is overexpressed in several types of cancer, and is a member of the family of insulin-like growth factor 2 mRNA binding proteins." (PMID 26416451, 2015). "IGF2 mRNA binding protein 3 (IGF2BP3) is an mRNA binding protein and cancer testis protein that regulates the translation of IGF2." (PMID 26244168, 2015). "We also observed transcriptional upregulation of IGF2 in cancer cells after IGF-1R blockade by monoclonal antibody." (PMID 26465273, 2015). "IGF2 has been shown to be deregulated in neurodevelopmental disorders, obesity and cancer, and is also known to have a critical role in memory consolidation in the brain." (PMID 26343731, 2015). "Immunofluorescence staining of cancer cells treated with cixutumumab revealed an increased level of IGF-2 production." (PMID 26465273, 2015). "Silencing IGF-2 or STAT3 expression in cancer cells or IGF-2R or CXCL8 expression in stromal cells significantly inhibits the cancer–stroma communication and vascular endothelial cells' angiogenic activities." (PMID 26465273, 2015). "The differentially methylated region (DMR) located upstream of the imprinted promoters of IGF2 exhibits plasticity under environmental stress and is hypomethylated in several types of cancer." (PMID 26343731, 2015). "ABCB1, BRCA1, GSTP1, and IGF2 displayed both an increased CM fraction and hyper-methylation in cancer." (PMID 26659027, 2015). "Loss of imprinting (LOI) is a common epigenetic event in cancer and a LOI of IGF2 has been reported in UBC." (PMID 26646822, 2015). "IGF2 had increased level in the malignant tumors, confirming previous microarray studies on the same material." (PMID 24498411, 2014). "This is associated with a number of hereditary overgrowth conditions, including Beckwith-Wiedemann syndrome and cancer that exhibits cell overgrowth resulting from IGF2 overexpression." (PMID 25364428, 2014). "In our earlier studies, miR-483 was identified as an oncogenic factor in cancer cells, which is similar to its host gene Igf2." (PMID 24801603, 2014). "We assessed the expression of 18 partners associated with the IGF signaling pathway, including receptors, IGFBPs, Akt, PI3K and Erk isoforms, by quantitative RT-PCR in 10 IGF2-low and the 23 IGF2-high carcinoma." (PMID 25089899, 2014). "Excess autocrine/paracrine production of IGF-1 and IGF-2 and/or low IGFBP3 levels are associated with an increased cancer risk of several cancers including breast, endometrial and bladder." (PMID 23826179, 2013).
cancer (continued). "We confirmed the growth factor IGF2 to be an excellent marker for differentiating between carcinomas and ACAn." (PMID 23925558, 2013). "Although IRB recognizes only insulin, its splice variant, IRA, which is most commonly expressed by tumors, also binds to IGF-2 with high affinity, resulting in mitogenic effects and increased survival, motility, and invasiveness of cancer cells." (PMID 22952934, 2012). "Among the IGF family proteins, IGF-1, IGF-1R and IGF-2 are positively correlated to cancer formation." (PMID 23071652, 2012). "The fetal transcription factor PLAG1 is found to be overexpressed in cancers, and has been suggested to bind the insulin like growth factor 2 (IGF2) P3 promoter, and to activate the IGF2 gene." (PMID 23023303, 2012). "A previous study proposed that higher IGF1 serum levels and lower IGFBP3 levels were associated with cancer risk; however, the intra-individual variability in circulating IGF1, IGF2, and IGFBP3 levels is genetically determined." (PMID 22347413, 2012). "IGF2, a growth-promoting, mitogenic and anti-apoptotic factor, plays a key role in the initiation and progression of several cancers." (PMID 22662119, 2012). "LOI exists in a wide variety of tumors, and although more investigations are required for future use, our preliminary data support the use of oncolytic viruses in the context of the IGF2 LOI system as a novel approach for cancer therapy." (PMID 23171475, 2012). "Based on early studies of our group and others, the transcriptional regulatory sequences of the H19 and IGF2 genes emerged as candidates for cancer targeted therapy." (PMID 21162716, 2010). "Since 2001 several more reports of a relationship between IGF-1, IGF-1 receptors, and cancer risk have been published as well as associations between IGF-2 and IGF-2 receptors and cancer risk." (PMID 20617018, 2010). "For example, loss of imprinting that leads to enhanced expression of the insulin-like growth factor 2 (Igf2) is frequently observed during cancer progression." (PMID 19194500, 2009). "A variety of epigenetic alterations in human cancers include global DNA hypomethylation, gene hypomethylation and promoter hypermethylation, and IGF2 LOI." (PMID 19737423, 2009). "Study showed the overexpressed IGF2 gene is a growth factor for tumors mediated through both the paracrine and autocrine pathways in human cancers." (PMID 19737423, 2009). "Transcription of IGF2 and H19 is developmentally down regulated in most adult tissues but reactivated in various cancers." (PMID 19956766, 2009). "While LOI of IGF2 leads to cancer through upregulation of the Wnt3 pathway." (PMID 41890909, 2026). "In addition, HIF-1α regulates the expression of nitric oxide synthase and insulin-like growth factor 2 (IGF2), which plays a key role in the proliferation and survival of cancer cells." (PMID 41515435, 2025). "Moreover, various pro‐inflammatory markers i.e., IL‐1, IL‐6, TNF‐α, IFN‐γ, TGF‐β and growth factors (VEGF, EGF, IGF‐2) are also involved in cancer progression." (PMID 40755497, 2025). "E2F3 is the only E2F member that is linked to cancer and is a potent and direct regulator of Igf2, with its role in adipose tissue still not clear." (PMID 41361331, 2025). "The phosphoinositide 3-kinase (PI3K)/Akt signaling pathway is involved in hypoxia-ischemia and it is a major signaling pathway in various types of cancer controlling cell survival, metastasis, and metabolism increasing the production of insulin-like growth factor 2 (IGF2)." (PMID 40963621, 2025). "Finally, we investigated a potential relationship between fibroblast IGF2 expression and clinical outcomes in patients with cancer." (PMID 39545420, 2024). "Insulin-like growth factor 2 (IGF2) is among the most studied genes affected by LOI in cancers." (PMID 38812777, 2024). "Previous studies support the idea that IGF2 activates a bias signaling through the IR-A that may play a distinct role in the growth of fetal tissues and cancer cells." (PMID 38521788, 2024).
cancer (continued). "The ligands for IGF1R (IGF1 and IGF2) are differentially expressed across pediatric cancers." (PMID 39510293, 2024). "The upregulation of IR-A enhances the mitogenic response of cancer cells to insulin and IGF-2, indicating that these isoforms could serve as potential targets for anti-cancer therapies." (PMID 38731097, 2024). "Notably, oHSV-D11mt binds mouse IGF2 more weakly than human IGF2, resulting in low cytotoxicity against mouse cancer cells." (PMID 38853689, 2024). "Consistent with our findings from multiple mouse models, these clinical data further support the notion that IGF2 contributes to immune evasion and may serve as a prognostic indicator and therapeutic target for various cancers." (PMID 39545420, 2024). "For example, IGF2 inhibitors have been shown to reduce the growth of IGF2-dependent cancers." (PMID 39830039, 2024). "Thus, targeting the IGF-2 signaling pathway is being investigated as a possible therapeutic approach for the treatment of cancer." (PMID 39064802, 2024). "Despite the intensive studies on the role of IGF2 in cancer, whether IGF2 is responsible for the activation of CAFs is not fully elucidated." (PMID 39759028, 2024). "According to these findings, we can speculate that the activation of the IGF2-Id1-IGF2 loop stimulates chronic aberrant IFN signaling in cancer cells, which contributes to stem-like phenotype and chemoresistance." (PMID 36672737, 2023). "Numerous studies suggest that the overactivation of the IR-A pathway, induced by insulin and IGF-2, plays a direct and crucial role in cancer development and may contribute to resistance against various anti-cancer drugs." (PMID 37834454, 2023). "This suggests that promoter usage (both for IGF2 and other cancer-driving genes) is cancer-type-specific and/or it may reflect the specific tumorigenic stage (specifically, early/partially differentiated versus advanced/fully dedifferentiated)." (PMID 37371750, 2023). "Therefore, as discussed for the IGF2 overexpression syndromes, the relaxation of their imprinting status can play a promoting role in IGF2 activation, as confirmed in a set of cancers displaying LOI." (PMID 37371750, 2023). "IGF2 is a known target of miRNAs, such as miR-100 and miR-125b in embryonic and cancer cells." (PMID 36672737, 2023). "Herein, we focus on evidence that suggests that IGF2 provides a crucial contribution to different hallmarks of the metastatic process, such as stem-like cell phenotypes, the generation of a pre-metastatic niche, and cancer immunoevasion." (PMID 36672737, 2023). "Elevated levels of IGF-1 and IGF-2 are related to various cancers, including EC." (PMID 36761024, 2023). "However, the role of IGF2 in cancer progression is certainly less characterized when compared to IGF1 and insulin." (PMID 36672737, 2023). "Overall, the body of these studies provides a strong rationale for exploring therapeutic strategies for advanced cancers, where IGF2 blockade could be used in combination with other approaches, including immunotherapy." (PMID 36672737, 2023). "Its mechanistic involvement in IGF2-driven cancers requires further attention." (PMID 37371750, 2023). "Notably, transcription factors implicated in promoting and maintaining cell stemness also stimulate the autocrine production of IGF2 by cancer cells." (PMID 36672737, 2023). "Furthermore, E2F3-overexpressing cancer cell lines display increased IGF2 expression, which can provide an LOI-independent mechanism for IGF2 regulation in cancer." (PMID 37371750, 2023). "The IGF-2/IR-A loop encourages cancer cell growth, migration, and self-renewal." (PMID 37834454, 2023). "Finally, certain cancer lines can alter the imprinting status of genes, in particular genes with tumor-suppressor properties like IGF2 and PEG3." (PMID 38002994, 2023). "Interestingly, IGF2 was the factor predominantly involved in maintaining cancer cell stemness through a paracrine mechanism involving the IGF1R/Nanog pathway." (PMID 36672737, 2023).